LEP (leptin)
Diseases named in the same sentence as LEP in open-access papers (continued):
Sharing a sentence is not in itself a finding about the gene and the disease.
Obesity (continued). "This could be caused by defective leptin transport across the blood–brain barrier into the CSF via tanycytes, as seen in various animal models at early stages of diet-induced obesity." (PMID 39047908, 2024). "Interestingly, seven of eight heterozygotes carrying the 80 kb deletion were overweight, which is consistent with previous observations that heterozygous human carriers of leptin or leptin receptor mutations are predisposed to overweight and obesity." (PMID 39771044, 2024). "Of note, obesity is associated with dysfunction in the circadian rhythms of appetite-regulating hormones, including delayed secretion of leptin from adipose depots, which may contribute to altered patterns of food intake." (PMID 39055386, 2024). "Baring complex biology, our finding that obesity is associated with increased leptin and IL-6 supports the observed effect of patient BMI on cancer cell invasiveness and migration, because these two adipokines stimulate breast cancer migration and invasiveness." (PMID 39408921, 2024). "Leptin is secreted from fat cells and associated with energy metabolism and obesity." (PMID 39642055, 2024). "For instance, studies in obese and leptin-deficient mouse models (ob/ob and db/db) suggest leptin might protect against LV hypertrophy during the progression of obesity." (PMID 39199415, 2024). "Further research focusing on revealing the underlying mechanism of leptin resistance induced by inflammatory mediators in CP will facilitate the design of drugs to block the pathways associated with impaired metabolism and ameliorate obesity." (PMID 38965454, 2024). "Addressing leptin resistance in the hippocampus may not only help mitigate cognitive decline but could also alleviate obesity-related comorbidities, including the risk of neurodegenerative diseases." (PMID 39594988, 2024). "For adults with obesity, combining regular aerobic exercise with a Mediterranean diet may be an effective strategy not only for body mass loss but also for improving leptin sensitivity and metabolic health." (PMID 39444577, 2024). "Leptin is an obesity-associated molecule functioning both as a hormone and a cytokine." (PMID 39073818, 2024). "Similar findings were observed with Bifidobacterium longum PI10, Bifidobacterium animalis, and Lactobacillus gasseri for 12 weeks, where the selected probiotics decreased body weight gain, fat deposition, obesity-linked metabolic dysfunction, and pro-inflammatory adipokines (IL-10 and leptin)." (PMID 38732619, 2024). "Insulin and leptin are associated with the development of obesity." (PMID 39906039, 2024). "As a result, women with obesity and leptin resistance face a higher risk of early pregnancy loss." (PMID 39767708, 2024). "Some factors related to obesity, such as insulin resistance and elevated levels of leptin, may contribute to pregnancy loss." (PMID 38883610, 2024). "We observed relatively large indirect effects mediated by circulating leptin and adiponectin, which may suggest a major role for these molecules in the pathway connecting obesity and CRC risk." (PMID 38644195, 2024). "Many animal models of monogenic obesity are linked to mutations in leptin or its receptors." (PMID 39963180, 2024). "IL-1β may also increase the expression of leptin mRNA in adipose tissue, adding to the underlying causes of obesity development." (PMID 38178093, 2024). "Additionally, leptin resistance intensifies addictive-like behaviors associated with overeating, establishing a detrimental cycle that exacerbates obesity and further impairs hippocampal function." (PMID 39594988, 2024). "One hormone commonly examined is leptin, an adipocyte-derived hormone known for controlling the regulation of food intake and energy balance, which has been associated with weight gain during infancy and early-life programming of obesity." (PMID 38474842, 2024).
Obesity (continued). "Therefore, this creates a feedback loop in which leptin creates insulin resistance that leads to obesity and obesity causes leptin production eventually leading to beta-cell failure." (PMID 38707092, 2024). "Moreover, leptin contributes to the maintenance of insulin resistance, which is associated with obesity-associated diseases." (PMID 38255203, 2024). "Adipokines, such as adiponectin and leptin, but also ceruloplasmin, have been linked to systemic inflammation, with adipogenesis contributing to the production of pro-inflammatory cytokines in obesity." (PMID 38256185, 2024). "Furthermore, a high-fat diet as a risk factor for obesity has been linked to early puberty, possibly induced by elevated serum levels of estradiol and leptin, and the activation of GnRH via hypothalamic microglial cells and phoenixin action." (PMID 38535297, 2024). "Furthermore, adipose tissue secretes adipocytokines, such as leptin and adiponectin, with increased serum leptin and decreased serum adiponectin levels being the hallmark characteristics of obesity." (PMID 38892352, 2024). "However, in animal studies, high-fat diet fed aged female mice showed an increase in the adiponectin/leptin ratio that protected the female from obesity and its associated cardiovascular events compared to males of the same age." (PMID 40988882, 2024). "Leptin deficiency results in hyperphagia and severe early-onset obesity." (PMID 39526054, 2024). "Obesity and related abnormalities may impair the brain glucocorticoids, leptin, and insulin receptor signaling that are linked to depressive symptoms." (PMID 38418418, 2024). "Our data support the model that melanocortin agonists could be useful in the context of sepsis and obesity, where leptin and melanocortin signaling may already be deficient." (PMID 38992428, 2024). "Given that leptin resistance is a known factor in the development of obesity, yet still not fully understood, our findings on improved leptin responsiveness could represent underlying mechanisms important for obesity treatment." (PMID 39183855, 2024). "Similarly, in humans, when the leptin hormone is deficient due to a gene mutation, it leads to obesity like in ob/ob mice." (PMID 38707092, 2024). "Moreover, recent research findings indicate that insufficient sleep is linked to obesity owing to a decrease in the hormone leptin, which suppresses appetite, and an increase in the hormone ghrelin, which stimulates appetite." (PMID 38542746, 2024). "Leptin and adiponectin dysregulation that occurs in obesity may have a role in obesity-associated colorectal cancer whereby high leptin levels are associated with an increased colon cancer risk." (PMID 39845239, 2024). "Leptin loss-of-function missense variants have been described in humans with severe obesity." (PMID 39002670, 2024). "Leptin was independently associated with both obesity and T2D." (PMID 38541912, 2024). "However, obesity is often associated with defective leptin signaling and a resistance to its typical anti-steatotic effect, leading to the development of hepatic steatosis." (PMID 38613062, 2024). "Leptin is encoded by the obesity gene and is mainly secreted by white adipocytes." (PMID 39427492, 2024). "Obesity-associated leptin dysregulation also alters alveolar macrophage activity and leukotriene production, which may explain why obese asthmatics respond differently to corticosteroids but benefit from leukotriene modifiers." (PMID 40474934, 2024). "Low HDL-C levels and elevated levels of TG are both linked to obesity-related inflammation, which, together with the subsequent disruption in leptin signaling, might contribute to a shared biological mechanism between obesity and mood dysregulation." (PMID 38564219, 2024). "Causing leptin resistance to exacerbate obesity, one risk factor of CAD." (PMID 39012662, 2024).
Obesity (continued). "Moreover, obesity-associated alterations in inflammation and adipokine signaling, including elevated leptin levels and reduced adiponectin, further promote tumor growth and metastasis." (PMID 39456156, 2024). "A Chinese family with early-onset obesity underwent LEP mutational screening via direct sequencing." (PMID 39041042, 2024). "In addition, obesity-associated hyperliptinemia and leptin resistance hamper muscle fatty acid oxidation and decrease lipolysis." (PMID 39335642, 2024). "Obesity has been identified as a significant risk factor for cataract formation, thought to be mediated through increases in reactive oxygen species and high circulating leptin in these patients, clouding the lens over time." (PMID 38678114, 2024). "However, obesity and metabolic syndrome have been associated with leptin resistance, partly because of abnormalities in leptin receptor signaling and impaired leptin transport across the blood–brain barrier." (PMID 39700087, 2024). "In addition, obesity caused by melanocortin receptor or leptin deficiency results in reduced ENHO mRNA expression in the liver." (PMID 39474256, 2024). "Increased leptin expression has also been linked to obesity-asthma." (PMID 39065704, 2024). "It has been hypothesized that exposure to elevated leptin levels could lead to the development of leptin resistance, subsequent alterations in appetite regulation and an increased risk of obesity." (PMID 38668349, 2024). "A series of features commonly associated with obesity, such as hyperglycemia, raised levels of plasma lipids and leptin, chronic low-grade inflammation, and altered response to muscle activity, has been associated with the presence of oxidative stress in obesity." (PMID 38247541, 2024). "An increase in leptin and visfatin which reflect body fat mass, and a concomitant decrease in adiponectin level may contribute to the pathogenesis of obesity-linked metabolic and cardiovascular complications." (PMID 39268361, 2024). "Several studies demonstrated that leptin or its receptor deficiency causes rare, autosomal recessive forms of severe, early-onset obesity, furthermore, obese patients with leptin receptor mutation have poor weight loss or significant weight regain after metabolic surgery." (PMID 38302999, 2024). "Comparatively, leptin resistance is a key mechanism underlying obesity, which may increase the risk of AD." (PMID 38290839, 2024). "Instead, other studies found a strong association LEP AA, GA and obesity." (PMID 39203789, 2024). "Therefore, the results obtained in this study cannot be directly translated to patients, although there are some rare congenital LEPR or leptin mutations in humans that can lead to overeating, obesity, and T2DM." (PMID 39317805, 2024). "Additionally, imbalances of salivary hormones, such as higher levels of insulin and leptin, have been associated with obesity in children, while these hormones, among others, are also involved in taste sensation." (PMID 39203770, 2024). "Leptin, a vital hormone regulating body energy and food intake, is also closely linked to obesity." (PMID 39281006, 2024). "It has been linked to an increased risk of obesity, which may affect the metabolism of insulin and glucose, accelerate leptin production or secretion, and enhance leptin resistance." (PMID 38672736, 2024). "There are a number of physiological and metabolic changes associated with obesity that may contribute to increased leptin levels." (PMID 39684379, 2024). "Interestingly, obesity, a key precursor to IR, is linked to adipose tissue dysfunction, chronic inflammation, and the imbalanced secretion of adipokines such as leptin and adiponectin, which diminish insulin sensitivity." (PMID 38791447, 2024). "By clarifying leptin’s regulation of lipids and glucose metabolism in breast cancer cell migration, this work may inform development of therapies to reduce obesity-associated metastatic breast cancer." (PMID 39609706, 2024).
Obesity (continued). "We next sought to determine whether the anorexigenic effect of TriMetChalc could reverse leptin-deficiency-induced obesity." (PMID 39337328, 2024). "Consequently, leptin-deficient (ob/ob) mice are widely used to study obesity and related hepatic complications." (PMID 39201365, 2024). "Whether the alterations in the microbial community within the stomach are linked to a high-fat diet, correlated with gastric leptin, or relate to human gastric carcinogenesis in obesity requires further exploration." (PMID 38075398, 2024). "Finally, myr-PrRP20 or palm-PrRP31 was chronically SC injected into DIO mice for 2 weeks; this treatment resulted in significant weight loss and improved metabolic parameters related to obesity, such as decreased leptin or insulin levels." (PMID 38577975, 2024). "Moreover, leptin stimulates macrophage proliferation in a dose-dependent manner, suggesting that high levels of leptin associated with obesity can enhance the proliferation and activation of ATMs." (PMID 39457523, 2024). "Another alteration associated with obesity is an increase in plasma leptin levels." (PMID 38840158, 2024). "Notably, obesity is associated with hyperleptinemia and leptin resistance, which compromises its effect on satiety and metabolic functions, making the reduction in leptin levels beneficial." (PMID 39334752, 2024). "In summary, treatment involving both leptin and calcitriol may reduce oxidative stress caused by impaired lipid clearance and obesity by upregulating hepatic LSR while limiting leptin-induced oxidative stress." (PMID 38892018, 2024). "The mechanisms underlying leptin resistance in obesity remain incompletely understood." (PMID 39872508, 2024). "This reduction in estradiol production, along with the deleterious consequences of leptin resistance and decreased gonadotropin signaling, may cause subfertility or infertility, particularly in women with obesity." (PMID 39595164, 2024). "Some evidence suggests that central leptin resistance causes obesity and that obesity-induced leptin resistance may cause injury to peripheral tissues." (PMID 38933888, 2024). "Although genetic studies of obesity have identified multiple mutations and loci associated with obesity (e.g., the ob/ob mouse, which has mutations in the gene encoding for leptin), exploratory studies of genome-wide changes can help to leverage system-level gene expression changes." (PMID 39273278, 2024). "Adipose tissue levels in the blood increase sensitivity to leptin expression, which might explain the link between obesity and the risk of OC." (PMID 38899007, 2024). "However, leptin is also a key appetite-regulating hormone, whose deficiency will cause polyphagia and lead to obesity and diabetes." (PMID 39658574, 2024). "Leptin and its receptor are important pharmacological targets because an excess, deficiency, and resistance to leptin are linked to various human pathologies, including obesity, fertility, cancer, and autoimmune illnesses." (PMID 39125635, 2024). "In particular, cranial radiation affects the hypothalamic-pituitary axis, which may lead to growth hormone deficiency and leptin insensitivity, which could, in turn, put brain tumor survivors at risk for neuroendocrine diseases such as obesity." (PMID 38238862, 2024). "Therefore, obesity induced through either exposure to a HFD or genetic loss of leptin led to a substantial reduction in EPAS1 levels in aortic endothelium." (PMID 39234692, 2024). "Thus, alterations in leptin levels are highly associated with metabolic comorbidities such as obesity and diabetes." (PMID 39684379, 2024). "Interestingly, mice with a conditional deletion of Xbp-1 in neurons and glia are more susceptible to diet-induced obesity and become leptin-resistant." (PMID 38500817, 2024). "Mutations in LEP can lead to congenital leptin deficiency, resulting in severe obesity." (PMID 39777073, 2024).
Obesity (continued). "Moreover, H. pylori infection has been associated with elevated leptin and ghrelin levels, which can contribute to obesity and increase the risk of developing diabetes." (PMID 38256380, 2024). "As a metabolic pathogenic status, obesity is often accompanied by systemic chronic low-grade inflammation and elevated levels of immune markers such as leptin, IL-6, and TNF, which may influence tumor growth." (PMID 39165513, 2024). "This indicates that diminished levels of these vitamins might influence the genetic expression of leptin, potentially leading to leptin resistance and a heightened risk of obesity." (PMID 38391792, 2024). "So far, the underlying mechanisms of leptin resistance remain incompletely understood, with evidence suggesting that it is likely triggered by chronic inflammation-induced stress response and prolonged obesity-induced hyperleptinemia." (PMID 40302954, 2024). "Furthermore, an imbalance among adiponectin (anti-inflammatory), leptin, and resistin contributes to the development of moderate inflammation associated with obesity and increased adipose tissue cell necrosis." (PMID 38495901, 2024). "Low levels of leptin delay satiety while eating, causing excessive nutrient intake and obesity." (PMID 38971751, 2024). "It was suggested that leptin acts as a circulating signal to control fetal homoeostasis, and higher leptin levels may increase the risk of obesity in offspring exposed to GDM." (PMID 38791090, 2024). "Often, impaired glucose tolerance and changes in melatonin, adiponectin, and leptin secretion, along with alterations in the clock gene functions in subjects with evening preferences, may be predisposed to obesity." (PMID 39796515, 2024). "Furthermore, there is now an extension trial for up to 5 years to study the safety and tolerability of continued setmelanotide in patients with obesity associated with genetic defects upstream of the MC4R in the leptin–melanocortin pathway." (PMID 39526054, 2024). "Obesity is associated with high plasma leptin concentration and leptin resistance." (PMID 38172970, 2024). "Leptin has been verified to be positively associated with body fat levels and obesity." (PMID 39139641, 2024). "Herein, we found that in leptin global knockout mice (ob/ob mice), hypothalamic p62 signaling partially reversed the obesity-phenotype caused by leptin deficiency, indicating that its anti-obesity effect is at least partially leptin-independent." (PMID 39479445, 2024). "This restricted application may arise from the fact that disrupted leptin and receptor expression frequently result in leptin resistance, a crucial factor in the development of complications associated with obesity." (PMID 38397015, 2024). "are regulated by obesity-associated leptin signaling, including SERPINE1 and VEGFA." (PMID 39439572, 2024). "Novel compound heterozygous mutations in LEP (NM_002303.3) are responsible for obesity." (PMID 39041042, 2024). "Obesity is a well-established risk factor for postmenopausal breast cancer, and any artificial sweetener-induced changes in leptin and ghrelin levels may have implications for breast cancer risk through obesity-related mechanisms." (PMID 39767777, 2024). "Obesity is also associated with the secretion of pro-inflammatory cytokines, such as interleukin-6 (IL-6) and tumor necrosis factor alpha (TNFα), as well as adipokines like leptin." (PMID 39767718, 2024). "Surprisingly, the blood leptin level is favorably linked with obesity." (PMID 39015860, 2024). "Additionally, certain adipocytokines associated with obesity, such as adiponectin and leptin, have been reported to correlate with the development of hyperuricemia." (PMID 38254222, 2024). "Research has shown higher serum TNF-α levels in obese individuals than in individuals with normal weight.This physiological activity may be associated with the action of leptin produced during obesity." (PMID 39564133, 2024).